TUBB8B (tubulin beta 8B)
Description:
Tubulin is the major constituent of microtubules, a cylinder consisting of laterally associated linear protofilaments composed of alpha- and beta-tubulin heterodimers. Microtubules grow by the addition of GTP-tubulin dimers to the microtubule end, where a stabilizing cap forms. Below the cap, tubulin dimers are in GDP-bound state, owing to GTPase activity of alpha-tubulin.
Synonyms: TUBB8P12
Tractability: Small molecule: a drug acting on it is in phase 2 or 3 trials; a high-quality ligand is known; it belongs to a druggable protein family. PROTAC: ubiquitination databases record sites on it; a small molecule that binds it is known.
Safety:
Unwanted effects reported when the protein is acted on. In parentheses: how it was acted on, where the effect was seen, and who reports it.
Increase, Aneuploid offspring (source: AOP-Wiki)
Gene: Protein-coding gene on chromosome 18 (47,221 to 73,545, reverse strand). Ensembl gene ENSG00000173213.
Subcellular location: Cytoplasm, cytoskeleton
Subcellular location (Human Protein Atlas): Microtubules; Basal body; Cytokinetic bridge; End piece; Flagellar centriole; Mitotic spindle; Primary cilium; Primary cilium tip; Principal piece
Pathways (Reactome):
Cell Cycle: EML4 and NUDC in mitotic spindle formation; Mitotic Prometaphase; Recruitment of NuMA to mitotic centrosomes; Resolution of Sister Chromatid Cohesion; Sealing of the nuclear envelope (NE) by ESCRT-III; Separation of Sister Chromatids; The role of GTSE1 in G2/M progression after G2 checkpoint
Vesicle-mediated transport: COPI-dependent Golgi-to-ER retrograde traffic; COPI-independent Golgi-to-ER retrograde traffic; COPI-mediated anterograde transport; Gap junction assembly; Microtubule-dependent trafficking of connexons from Golgi to the plasma membrane; Translocation of SLC2A4 (GLUT4) to the plasma membrane
Immune System: MHC class II antigen presentation; PKR-mediated signaling
Neuronal System: Activation of AMPK downstream of NMDARs; Assembly and cell surface presentation of NMDA receptors
Signal Transduction: RHO GTPases Activate Formins; RHO GTPases activate IQGAPs
Autophagy: Aggrephagy
Cellular responses to stimuli: HSP90 chaperone cycle for steroid hormone receptors (SHR) in the presence of ligand
Developmental Biology: Recycling pathway of L1
Disease: HCMV Early Events
Hemostasis: Kinesins
Metabolism of proteins: Carboxyterminal post-translational modifications of tubulin
Organelle biogenesis and maintenance: Cargo trafficking to the periciliary membrane
Gene Ontology:
Molecular function: GTP binding; structural constituent of cytoskeleton; GTPase activity
Biological process: mitotic cell cycle; cytoskeleton organization; microtubule-based process
Cellular component: extracellular exosome; cytoskeleton; microtubule
Genetic constraint (gnomAD): Loss-of-function variants: 17 observed, 17.52 expected, observed/expected ratio (o/e) 0.97, 90% interval 0.66 to 1.45. The upper end of that interval is the gene's LOEUF score, 1.45, which puts it in group 6 of 6, group 1 being the genes least tolerant of losing a copy. Missense variants: 417 observed, 397.92 expected, observed/expected ratio (o/e) 1.05, 90% interval 0.97 to 1.14. Synonymous variants: 149 observed, 136.15 expected, observed/expected ratio (o/e) 1.09, 90% interval 0.96 to 1.25.
Homologues: Paralogues in human: TUBB8 (96% identical), TUBB4B (89% identical), TUBB4A (88% identical), TUBB2B (87% identical), TUBB (87% identical), TUBB2A (87% identical), TUBB3 (85% identical), TUBB6 (84% identical), TUBB1 (75% identical), TUBA1B (42% identical), TUBA1A (42% identical), TUBA1C (41% identical), and 11 more.
Diseases named in the same sentence as TUBB8B in open-access papers:
TUBB8B is named in the same sentence as 1 disease in open-access papers, as found by Europe PMC text mining. Sharing a sentence is not in itself a finding about the gene and the disease.
TUBB8B shares sentences with these, for which no sentence is quoted: cancer (1 paper).